IFIT1 (interferon induced protein with tetratricopeptide repeats 1)
Diseases named in the same sentence as IFIT1 in open-access papers (continued):
Sharing a sentence is not in itself a finding about the gene and the disease.
breast carcinoma (17 papers, 2013 to 2025). "A study reported that high levels of IFIT1 mRNA were associated with radiation resistance in breast cancer." (PMID 29681787, 2018). "ST_7 showed higher gene expression of interferon (IFN)‐inducible genes such as ISG15, IFIT1 and IFI6, which were recently demonstrated to be associated with ER+ breast cancer therapy resistance." (PMID 38282415, 2024). "Both breast cancer and melanoma BrM cells enhanced the expression of IFIT1 and Ubiquitin Like Modifier (ISG15) in the cocultured astrocytes." (PMID 37149684, 2023). "Six hub genes, including IFIT1, ISG15, IFI6, GOLM5, KLHL35, and OAS2, were associated with the total survival probability in breast cancer patients." (PMID 30646630, 2019). "utilized scRNA-seq technology to identify three functionally heterogeneous subpopulations of TANs in breast cancer: Neutrophil_IFIT1, Neutrophil_DUSP6, and Neutrophil_S100A1.The IFIT1+ subpopulation exhibits high expression of ISG15, MX1, and IFIT1, demonstrating antigen-presenting capabilities." (PMID 40568594, 2025). "Notably, our findings indicate that the genes upregulated by O-desmethyltramadol in both breast cancer cell lines—IFIT1, GBP4, SECTM1, and OASL—are regulated by interferon." (PMID 40362379, 2025). "In addition, our analysis identified an IFN-responsive neutrophil population with high expression of IFN-responsive genes (Ifit3, Ifit1, Ifit3b, Ifi47, Ifitm3, Rsad2, Isg15, and Isg20), which is more present in metastatic lung of breast cancer." (PMID 37483625, 2023). "Our data suggest that several pathway members, such as Stat1, Ifngr2, Tgtp1, Ifit1, Gbp1 and Gbp3, may be suitable biomarkers for residual disease in breast cancer patients treated with cytotoxic chemotherapy." (PMID 23520493, 2013). "In some cancers, such as breast cancer and hepatocellular carcinoma (HCC) the role of IFIT1 in cancer biology is controversial, with evidence somewhat skewed towards supporting its role as a favorable prognostic factor." (PMID 40564154, 2025). "IFIT1, which was significantly overexpressed in all four malignant TIS cell types, has been shown to be significantly upregulated in residual breast cancer tumors." (PMID 40312750, 2025). "In early-stage breast cancer patients treated with breast-conserving surgery and radiation therapy with or without chemotherapy and/or adjuvant hormone therapy, IFIT1 protein has been shown to act as a favorable prognostic marker for local control." (PMID 40564154, 2025). "Accordingly, high IFIT1 and IFIT3 expression have been correlated with a better therapeutic response to IFNs along with chemotherapeutics and immunostimulating agents in patients with breast cancer, glioblastoma, and hepatocellular carcinoma." (PMID 31921891, 2019). "IFIT1 and IFIT3 genes are classified as IRDS subset genes and are considered as predictive biomarkers for chemotherapy and radiation therapy in many primary human cancers, such as breast cancer, head and neck cancer, prostate cancer, lung cancer, and glioma." (PMID 31921891, 2019).
melanoma (15 papers, 2017 to 2025). A malignant, usually aggressive tumor composed of atypical, neoplastic melanocytes. "Drug sensitivity analysis suggested that high expression levels of IFIT1 in melanoma are associated with increased sensitivity to the tyrosine kinase inhibitor, dasatinib and positively correlated with the level of immune cell infiltrates and markers." (PMID 40564154, 2025). "Cytokine profiling of SPOP-depleted human melanoma A2058 cells revealed increased expression of interferon-stimulated genes (ISGs), including IFIT1, CXCL10, and MX1, which was validated by RT-PCR." (PMID 41148213, 2025). "In melanoma patients treated with anti-PD1 and cetirizine combination therapy, upregulations of IFI27, IFIT1, and IFIT3 are associated with M1 polarization of macrophages and improved patient outcome." (PMID 37174688, 2023). "IFIT1 also enhanced targeted therapeutics and immunotherapy in melanoma." (PMID 40564154, 2025). "More recently, ganetespib was demonstrated to potentiate anti-tumor effect of immunotherapy as it sensitized melanoma cells to T-cell-mediated killing by upregulating interferon response genes, IFIT1, IFIT2, IFIT3 (interferon-induced protein with tetratricopeptide repeats 1–3) in vitro and in vivo." (PMID 31659567, 2020). "In SKCM, low expression levels of IFIT3, similar to IFIT1 and IFIT2, have been found to be correlated with patients’ poor overall survival and DSS and decreased sensitivity of melanoma cells to dasatinib and T-cell killing and apoptosis." (PMID 40564154, 2025). "Representative genes from this gene set such as Rsad2, Ifih1, Isg15, Ifit1 and Tmem173 were consistently found to be upregulated in all available NRF2 knockout melanomas." (PMID 32978520, 2020). "Conversely, overexpressing IFIT1, IFIT2 and IFIT3 in human melanoma cell lines enhanced the sensitivity of human melanoma cell lines to T-cell killing, thereby recapitulating the effects of ganetespib treatment." (PMID 28878208, 2017). "Similarly, MEK inhibition in KRAS-mutant lung cancer A549 cells and BRAF inhibition in BRAF-mutant melanoma A375 cells also increased IRF1 and IFIT1 protein levels (right)." (PMID 34535668, 2021). "Not much information is available concerning MX1 and MX2 during SARS-CoV-2 infection; however, in melanoma cell lines, it was reported that persistent IFN-γ stimulation increases the expression and genome occupancy of STAT1 and induces the expression of ISGs, such as IFIT1 and MX1." (PMID 36298734, 2022). "Additionally, the loss of IFN-γ pathway genes IFNGR1, IFNGR2, JAK2, IRF1, IFIT1, IFIT3, MTAP, miR31 and amplification of the suppressor genes SOCS1 and PIS4 have been shown in melanoma patients non-responsive to anti-CTLA4 therapy." (PMID 30186768, 2018). "Upregulation of interferon response genes in multiple melanoma cell lines by ganetespib was confirmed by quantitative real time PCR and Western blot analyses, most strongly for members of the IFN-induced protein with tetratricopeptide repeats (IFIT) gene family: IFIT1, IFIT2 and IFIT3." (PMID 28878208, 2017). "Melanoma patients lacking clinical responses to the anti-CTLA-4 immunotherapeutic, ipilimumab (as compared to those who had such responses) harbored a much higher rate of genomic defects in the IFN-γ pathway genes, including genetic losses of IFIT1, IFIT2 and IFIT3." (PMID 40564154, 2025).
influenza (13 papers, 2011 to 2025). An acute viral infection of the respiratory tract, occurring in isolated cases, in epidemics, or in pandemics; it is caused by serologically different strains of viruses (influenzaviruses) designated A, B, and C, has a 3-day incubation period, and usually lasts for 3 to 10 days. "Furthermore, this GO analysis indicated that genes associated with the antiviral response to influenza (e.g., Ifi27l2a, Isg20, Oas1a, Isg15, Ifit1, Oasl1, and Ifit3) were strongly enriched in mice vaccinated with WIV alone as compared with mice vaccinated with WT IL-1β or CD8α ALN-1." (PMID 32714571, 2020). "IFIT1, IFIT3, IFITM3, MX1, and ISG15 have all been shown to possess anti-influenza activities; however, a genetic variant of IFITM3 has been associated with severe influenza infection and higher hospitalization rate." (PMID 33347425, 2020). "Both ISG15 and IFIT1 are exemplars of well-described ISGs with known antiviral functionality in the setting of SARS-CoV-2, HCMV, and influenza infections." (PMID 40815167, 2025). "We next assessed expression levels of various cytokines and chemokines (i.e., IFNB1, IFNL1, IFNL2/3, IFIT1, IFIT3, OAS1, MX1, IL‐6, CXCL10, and IFITM1) which were triggered by influenza and OC43 virus infections alone or together by qPCR." (PMID 38556468, 2024). "In conclusion, IFIT1 and IFIT2 are anti-influenza proteins through their inhibitory effects on viral RNA synthesis." (PMID 37515100, 2023). "The aim of the study was to develop a multiplex qPCR system for simultaneous detection of MDA5, RIG-1, and IFIT-1 mRNA levels and to evaluate these genes’ expression in the white blood cells (WBC) of influenza and SARS-CoV-2 patients." (PMID 36298646, 2022). "The present work investigated the role of IFIT1–3 and IFI44 proteins in the cross-immunity effect observed between influenza and RSV." (PMID 33081322, 2020). "Using the assay, we discovered that RIG-1, MDA5 and IFIT-1 mRNA levels were augmented in the WBCs of influenza infected patients, but not in those from SARS-CoV-2 patients after 2 weeks from the disease onset." (PMID 36298646, 2022). "Furthermore, as IFIT1–3 and IFI44 were upregulated by influenza A, we hypothesized that they could be key players in RSV growth inhibition by influenza A." (PMID 33081322, 2020).
oral squamous cell carcinoma (13 papers, 2020 to 2026). "For example, overexpression of IFIT1 or IFIT3 increased oral squamous cell carcinoma (OSCC) resistance to multiple chemotherapeutic drugs, including 5FU, cisplatin, oxaliplatin, carboplatin." (PMID 37980495, 2023). "Consistent with past studies, the expression of IFIT1/2/3/5 was dysregulated in multiple types of human tumors, including bladder cancer, pancreatic cancer, oral squamous cell carcinoma and neck squamous cell carcinoma." (PMID 37980495, 2023). "IFIT1 expression has been shown to be positively related to the expression of p-EGFRY1068 in Oral Squamous Cell Carcinoma." (PMID 37817224, 2023). "Additionally, the cancer-promoting effects of IFIT1 have been reported in colorectal cancer, oral squamous cell carcinoma, and nasopharyngeal carcinoma (33, 34l 35)." (PMID 41267985, 2025). "In oral squamous cell carcinoma (OSCC), IFIT1 and IFIT3 promote metastasis, while IFIT2 exhibits the opposite effect." (PMID 36851555, 2023). "For example, induction of ISG15 or IFIT1 in human squamous cell carcinoma cancer cell line conferred doxorubicin chemo-resistance, or overexpression of IFIT1 and IFIT3 in oral squamous cell carcinoma (OSCC) promoted experimental metastasis." (PMID 35565392, 2022). "It has been reported that IFIT1 and IFIT3 are critical for EGFR recycling and activation in oral squamous cell carcinoma." (PMID 35280763, 2022). "IFIT1 and IFIT3 contribute to the metastasis of oral squamous cell carcinoma, and serve as prognostic markers for patients with this disease." (PMID 35280763, 2022). "Using the Toruner dataset (20 patient samples), we found that the expression of IFIT1, (p = 2.76 × 10−8) and ALOX5 (p = 0.0019) genes were high in oral squamous cell carcinoma (OSCC) compared to normal squamous cells." (PMID 32961854, 2020). "The study covering the role of IFIT1 and IFIT3 genes on drug resistance in OSCC cells (oral squamous cell carcinoma) showed that silencing of IFIT1 and IFIT3 by shRNA increased the sensitivity to cisplatin, thus further implicating their role in chemotherapy resistance." (PMID 33922087, 2021). "However, a prognostic significance in cancer has been suggested for IFITs and a novel role for IFIT1 and IFIT3 has been suggested in progression and metastasis in oral squamous cell carcinoma through interaction with annexin A2, which enhances recycling of the EGF receptor." (PMID 38447798, 2024).
hepatocellular carcinoma (10 papers, 2012 to 2025). A malignant tumor that arises from hepatocytes. "Low IFIT1 mRNA expression was correlated with poor DSS in hepatocellular carcinoma (HCC) patients with chronic hepatitis." (PMID 40564154, 2025). "Another study shows that silencing of IFIT1 increases HBV replication in hepatoma cells." (PMID 37515100, 2023). "To confirm the biological IFN activity of each sample, we stimulated the human hepatocellular carcinoma cell line, HepG2, with PASC patient serum and investigated the mRNA expression level of IFN-stimulated genes (ISGs) involving Mx1, ISG15, PKR, and IFIT1." (PMID 39921694, 2025). "To this end, we compared the expression of twelve genes either linked to the induction of innate immunity (STAT1, STAT2, PKR) or IFN effector genes (OAS1/2, IFIT1–3, RSAD2, MX1, TRIM14, ISG15) in HCV-infected hepatoma cells and mature iHLCs." (PMID 29497123, 2018). "Beyond that, we could also show that (iv) resminostat, after hepatoma cell stimulation with exogenous human interferon (IFN)-β, is able to prevent the induction of IFN-stimulated genes, such as IFIT-1." (PMID 27119111, 2015). "Therefore, we had to prestimulate hepatoma cells with exogenous human IFN-β (1,000 U/ml) for 24 hours, which then led to a significant induction of expression of both IFIT-1 and STAT1 and its phosphorylation (P-STAT1) in all three hepatoma cell lines (lane 2 in all panels)." (PMID 27119111, 2015). "However, when adding resminostat (5 μmol/l) on IFN-β prestimulated (1,000 U/ml) hepatoma cells, a profound suppression of IFIT-1 expression was observed in HepG2, Hep3B, and PLC/PRF/5 hepatoma cells, but no alteration in the phosphorylation status of STAT1 (lane 4 in all panels)." (PMID 27119111, 2015).
HIV-1 infection (10 papers, 2011 to 2025). The type species of lentivirus and the etiologic agent of acquired immunodeficiency syndrome (AIDS). "By contrast, ΔNef HIV-1 infection in iDCs increased IFIT1 mRNA levels 13- and 27-fold at 16 and 48 hr post-infection, respectively, compared with mock infection." (PMID 21504576, 2011). "Compared with mock infection, WT and ΔNef HIV-1 infections in iDCs resulted in a 5-fold increase of IFIT1 mRNA levels at 6 hr post-infection." (PMID 21504576, 2011). "Finally, we analyzed the expression of ISGs genes and showed a 1.41-fold increase in IFIT1 expression levels at mRNA 3 days after HIV-1 infection as compared with mock-infected cells." (PMID 41041557, 2025). "We also noted that HIV-1 infection induces a prominent antiviral state in early/mid-gestation HCs, characterized by transcription and secretion of IFN-α and significantly elevated transcription of the RLRs, STAT1, STAT5, ISG15, OAS1, IFIT1, IFIT2, IFIT3, and Viperin." (PMID 34432853, 2021). "As previously shown, HIV-1 infection of primary CD4+ T cells failed to induce or very weakly induced (in cells from donor I) type I IFN production and the IFN-responsive genes ISG15, IFIT1, and IFIT2." (PMID 37922361, 2023).
lupus (10 papers, 2014 to 2024). "A recent study of serologic and cytokine profiles in patients with systemic lupus erythematosus also demonstrated an association between an IRF8 variant (rs17445836) and decreased levels of IFIT1." (PMID 25880423, 2015). "The upregulated IFIT1 in lupus plays an important role in the production of cytokines IL-4 and IL-10, which may be related to the imbalance of Th1/Th2." (PMID 30836987, 2019). "Interferon-induced protein with tetratricopeptide repeats (IFIT) 1 is a member of the IFIT family and plays an important role in antiviral processes, and research has revealed that IFIT1 is involved in the development of systemic lupus erythematosus (SLE)." (PMID 36158807, 2022). "Lupus patients had low methylation and high expression of interferon regulatory genes, including BST2, IFIT3, IFI44L, and IFIT1." (PMID 38753689, 2024). "Similarly, IFIT1 and RSAD2 also have a critical function in lupus development." (PMID 34079550, 2021).
autoimmune disease (9 papers, 2010 to 2024). A disorder resulting from loss of function or tissue destruction of an organ or multiple organs, arising from humoral or cellular immune responses of the individual to their own tissue constituents. "In SIgAD patients with concomitant autoimmune diseases, decreased expression levels of genes related to the type I interferon (IFN) pathway, including IFIT1, MX1, IFI6, and IFI44L, were observed." (PMID 38474381, 2024). "Studies in the autoimmune disease rheumatoid arthritis, show T cells in RA patients when treated with mtDNA actually have lower IFNB and IFIT1 transcripts." (PMID 35223833, 2022). "Among ISGs, both ddx58 with IFIT1 and ISG15 with OAS1 showed significant positive correlations in all types of autoimmune disease and HC samples." (PMID 34848794, 2021). "Additionally, in agreement with a local immune suppression environment, IFIT1, OAS1 and OAS2 are up-regulated in the autoimmune disease systemic lupus." (PMID 20707927, 2010). "IFI44L, RADS2, and IFIT1 showed the highest fold changes and comparable increases in expression in active and inactive SLE patients; IFI44L is noteworthy as it has been reported to be predictive of SLE status relative to healthy controls and other autoimmune diseases." (PMID 34946847, 2021).
hepatitis C (8 papers, 2019 to 2025). "In addition, results of the KEGG functional enrichment analysis in the present demonstrated that IFIT1 was associated with hepatitis C. Patients with hepatitis C virus (HCV) infection have a greater risk of developing ACS than those without HCV infection." (PMID 34753383, 2021). "Single-cell RNA-seq analysis confirmed the impact of type I IFN on fibrosis progression, showing reduced expression of viral protein interaction genes (Ccl12, Xcr1) and hepatitis C-related genes (IFNg, Ifit1) in the Type I IFN blockade group." (PMID 40260261, 2025). "Therefore, IFIT1 may regulate the progression of ACS by regulating hepatitis C." (PMID 34753383, 2021). "In addition, the six upregulated DETGs are involved in Hepatitis C, including CDKN1A, TRAF3, CXCL10, CASP3, EIF2S1, and IFIT1." (PMID 37107704, 2023).
atherosclerosis (7 papers, 2021 to 2024). A disease characterized by the build-up of fatty material and calcium deposition in the arterial wall resulting in partial or complete occlusion of the arterial lumen. "Zhang found that circ_0086296 is upregulated in human carotid artery plaques and can promote ECs injury and atherosclerosis progression via an IFIT1/STAT1 feedback loop by sponging miR-576-3p." (PMID 37990246, 2023). "IFIT3, IFIT2 and IFIT1 were the top three proteins potentially playing key roles in atherosclerosis." (PMID 36437453, 2022). "IFIH1, IFIT1, IFIT2, IFIT3, ISG15 and OAS3 had similar expression differences to the training set and had good diagnostic abilities for atherosclerosis." (PMID 36437453, 2022). "Furthermore, IFIT1 promotes the expression of pro-inflammatory cytokines induced by lipopolysaccharide in human umbilical vein endothelial cells, indicating that IFIT1 is a key participant in the development of atherosclerosis." (PMID 35034537, 2022). "A previous study identified IFIT1, IFIT2, IFIT3, and ISG15 as immune-related hub genes of atherosclerosis." (PMID 38397063, 2024). "circ_0086296, together with miR-576-3p, IFIT1, and STAT1, constitutes a feedback loop that participates in the regulation of atherosclerosis progression, and high circ_0086296 expression was confirmed in the exosomes of serum of patients with atherosclerosis." (PMID 36803975, 2023). "Our study identified IFIH1, IFIT1, IFIT2, IFIT3, ISG15 and OAS3 as immune-related hub genes of atherosclerosis." (PMID 36437453, 2022). "Therefore, the circ_0086296/miR-576-3p/IFIT1/STAT1 feedback loop participates in atherosclerosis progression and contributes to the high circ_0086296 expression observed in the exosomes of serum of patients with atherosclerosis." (PMID 36138395, 2022).